DHX37 (DEAH-box helicase 37)
Description:
ATP-binding RNA helicase that plays a role in maturation of the small ribosomal subunit in ribosome biogenesis. Required for the release of the U3 snoRNP from pre-ribosomal particles. Part of the small subunit (SSU) processome, first precursor of the small eukaryotic ribosomal subunit. During the assembly of the SSU processome in the nucleolus, many ribosome biogenesis factors, an RNA chaperone and ribosomal proteins associate with the nascent pre-rRNA and work in concert to generate RNA folding, modifications, rearrangements and cleavage as well as targeted degradation of pre-ribosomal RNA by the RNA exosome. Plays a role in early testis development. Probably also plays a role in brain development.
Synonyms: DDX37; KIAA1517; MGC4322; MGC2695; Dhr1; NEDBAVC; SRXY11
Tractability: Small molecule: a structure with a bound ligand is known. PROTAC: ubiquitination databases record sites on it; its protein half-life has been measured.
Gene: Protein-coding gene on chromosome 12 (124,946,825 to 124,989,133, reverse strand). Ensembl gene ENSG00000150990.
Subcellular location: Nucleus, nucleolus; Cytoplasm; Nucleus membrane
Subcellular location (Human Protein Atlas): Nuclear membrane
Pathways (Reactome):
Metabolism of RNA: Major pathway of rRNA processing in the nucleolus and cytosol; rRNA modification in the nucleus and cytosol
Gene Ontology:
Molecular function: ATP hydrolysis activity; protein binding; U3 snoRNA binding; helicase activity; ATP binding; nucleic acid binding; RNA helicase activity
Biological process: brain development; positive regulation of male gonad development; ribosomal small subunit biogenesis; ribosome assembly; ribosome biogenesis; maturation of SSU-rRNA from tricistronic rRNA transcript (SSU-rRNA, 5.8S rRNA, LSU-rRNA)
Cellular component: cytoplasm; nuclear membrane; nucleolus; small-subunit processome; nucleoplasm
Genetic constraint (gnomAD): Loss-of-function variants: 52 observed, 126.43 expected, observed/expected ratio (o/e) 0.41, 90% interval 0.33 to 0.52. The upper end of that interval is the gene's LOEUF score, 0.52, which puts it in group 2 of 6, group 1 being the genes least tolerant of losing a copy. Missense variants: 1,343 observed, 1,532.3 expected, observed/expected ratio (o/e) 0.88, 90% interval 0.84 to 0.92. Synonymous variants: 634 observed, 642.75 expected, observed/expected ratio (o/e) 0.99, 90% interval 0.92 to 1.05.
Homologues: Orthologues: chimpanzee DHX37 (99% identical), macaque DHX37 (97% identical), mouse Dhx37 (84% identical), guinea pig DHX37 (84% identical), rat Dhx37 (83% identical), pig DHX37 (83% identical), rabbit DHX37 (79% identical), dog DHX37 (73% identical), tropical clawed frog dhx37 (68% identical), zebrafish dhx37 (65% identical), Drosophila melanogaster kz (46% identical), Caenorhabditis elegans rha-2 (41% identical). Paralogues in human: DHX8 (25% identical), DHX16 (24% identical), DHX38 (23% identical), DHX33 (22% identical), DHX35 (22% identical), DHX15 (22% identical), DHX57 (21% identical), DHX29 (21% identical), DHX34 (21% identical), YTHDC2 (20% identical), DHX30 (19% identical), DHX36 (19% identical), and 6 more.
Diseases named in the same sentence as DHX37 in open-access papers:
DHX37 is named in the same sentence as 52 diseases in open-access papers, as found by Europe PMC text mining. Sharing a sentence is not in itself a finding about the gene and the disease. The quoted sentences say what the papers report.
breast carcinoma (5 papers, 2020 to 2026). "In breast cancer, low cytoplasmic DHX37 protein expression was significantly associated with adverse clinicopathological parameters including larger tumour size, higher grade, lymphovascular invasion and positive nodal status (all P < 0.001)." (PMID 42151440, 2026). "Low DHX37 expression was associated with poor breast cancer-specific survival (P < 0.001), particularly among oestrogen receptor-positive patients." (PMID 42151440, 2026). "The result is consistent with previous findings that DHX37 upregulation is associated with poor prognosis in breast cancer." (PMID 33490273, 2021). "Tumor Immune Dysfunction and Exclusion (TIDE) analysis indicated that the high expression of DHX37 is associated with worse prognosis in breast cancer." (PMID 33490273, 2021). "Although DHX37 functions have not been extensively elucidated, it was once discovered that it suppressed T cell activation in breast cancer." (PMID 33490290, 2020).
cryptorchidism (3 papers, 2020 to 2025). The failure of one or both testes of a male fetus to descend from the abdomen into the scrotum during the late part of pregnancy. "The presenting phenotypes of children carrying pathogenic DHX37 pathogenic variants exist on a spectrum ranging from phenotypic females to males with bilateral or unilateral cryptorchidism." (PMID 31337883, 2020).
lung adenocarcinoma (3 papers, 2020 to 2022). A carcinoma that arises from the lung and is characterized by the presence of malignant glandular epithelial cells. "Notably, DHX37 expression is related to various immune infiltration levels in cancers, especially in liver cancer and lung adenocarcinoma." (PMID 33490290, 2020). "In addition, this study found that in liver hepatocellular carcinoma and lung adenocarcinoma, immune infiltration levels and various immune marker sets were correlated with the level of DHX37 expression." (PMID 33490290, 2020). "DHX37 could affect the prognosis of patients with HCC or lung adenocarcinoma by immune infiltration, and can be used as a prognostic biomarker for HCC and lung adenocarcinoma." (PMID 35836576, 2022). "Confirming the prognostic value of DHX37 in liver hepatocellular carcinoma (LIHC) and lung adenocarcinoma (LUAD), we explored the role of DHX37 in infiltrated lymphocytes in cancers using the Gene Expression Profiling Interactive Analysis (GEPIA) and TIMER databases." (PMID 33490290, 2020).
ovarian carcinoma (3 papers, 2020 to 2026). A malignant neoplasm originating from the surface ovarian epithelium. "DHX37 shows contrasting prognostic associations in breast and ovarian cancer, suggesting context-dependent biological functions." (PMID 42151440, 2026). "Reduced DHX37 expression may promote tumour progression in ER-positive breast cancer, but is associated with favourable outcomes in ovarian cancer." (PMID 42151440, 2026). "This study investigated the expression of DHX37 in large breast and ovarian cancer patient cohorts using immunohistochemistry in 1512 breast and 420 ovarian cancer cases and complementary transcriptomic datasets." (PMID 42151440, 2026). "In ovarian cancer, low DHX37 expression was associated with lower FIGO stage, absence of residual disease and improved overall survival (P = 0.013)." (PMID 42151440, 2026). "In addition, DHX37 only had significant correlation with RFS for pancreatic ductal adenocarcinoma and ovarian cancers." (PMID 33490290, 2020).
Testicular regression syndrome (3 papers, 2024 to 2025). Testicular regression syndrome (TRS) is a developmental anomaly characterized by the absence of one or both testicles with partial or complete absence of testicular tissue. "In DSD cohorts, DHX37 gene mutations have different detection frequencies (0.77%–45.45%), whereas in testicular regression syndrome and 46,XY gonadal dysgenesis cohorts, they have a high detection rate." (PMID 40026690, 2025). "In 2019, heterozygous missense variants in DHX37 (OMIM ∗617362) were described in individuals with 46, XY gonadal dysgenesis or testicular regression syndrome, becoming a new gene associated with 46, XY DSD." (PMID 38962685, 2024). "DHX37, a gene involved in ribosome biogenesis, located on chromosome 12, at the 12q24.31 region, has recently emerged as a contributor to 46,XY DSD, particularly gonadal dysgenesis and testicular regression syndrome (TRS)." (PMID 40766295, 2025).
breast invasive carcinoma (2 papers, 2020 to 2021). "In the present study, we found that the expression of DHX37 was significantly upregulated in 17 of 23 human cancers, including invasive breast cancer." (PMID 33490273, 2021). "Unlike the findings from PrognoScan, we found a high expression of DHX37 reduced survival in BRCA (breast invasive carcinoma) by using the Kaplan-Meier Plotter database." (PMID 33490290, 2020).
disorders of sex development (2 papers, 2024 to 2026). "So far, a total of 21 variants in DHX37 have been reported in 58 cases with 46,XY disorders of sex development (DSD)." (PMID 38769888, 2024). "So far, a total of 21 pathogenic variants in DHX37 have been reported in 58 cases with 46,XY disorders of sex development (DSD).Our finding further expands the spectrum of the DHX37 variant and could assist in the molecular diagnosis of 46,XY DSD patients." (PMID 38769888, 2024). "DHX37, a member of the DEAH-box family of RNA helicases, has been identified as a pathogenic gene in 46, XY disorders of sex development (DSD), underscoring its potential significance in testicular development." (PMID 41535247, 2026).
esophageal adenocarcinoma (2 papers, 2020 to 2021). A malignant tumor with glandular differentiation arising predominantly from Barrett mucosa in the lower third of the esophagus. "For esophageal adenocarcinoma, DHX37 was found to have a favorable effect on relapse-free survival while it worsened overall survival." (PMID 33490290, 2020).
gonadal dysgenesis (2 papers, 2020 to 2024). A congenital disorder characterized by the presence of extremely hypoplastic gonads preventing the development of secondary sex characteristics. "Based on our literature review, this is the first case with the combined presence of pathogenic mutations in the MAMLD1 gene and DHX37 gene in a patient with gonadal dysgenesis." (PMID 38962685, 2024). "We provide compelling genetic evidence that specific variants in the DEAH-box protein DHX37, which encodes a putative RNA helicase, are a frequent cause of nonsyndromic 46,XY gonadal dysgenesis as well as TRS." (PMID 31337883, 2020). "DHX37 pathogenic variants are a new cause of an autosomal dominant form of 46,XY DSD, including gonadal dysgenesis and TRS, showing that these conditions are part of a clinical spectrum." (PMID 31337883, 2020).
head and neck squamous cell carcinoma (2 papers, 2020 to 2021). A squamous cell carcinoma that arises from any of the following anatomic sites: lip and oral cavity, nasal cavity, paranasal sinuses, pharynx, larynx, and salivary glands. "However, DHX37 expression has less influence on head and neck squamous cell carcinoma." (PMID 33490290, 2020).
hepatocellular carcinoma (2 papers, 2020 to 2023). A malignant tumor that arises from hepatocytes. "Our study suggests that DHX37 is a novel prognostic marker for hepatocellular carcinoma and is valuable for predicting response to chemotherapy and immunotherapy." (PMID 37958405, 2023). "Previously, many studies have found that DHX9, DHX15, DDX24, DHX29, etc. are widely involved in tumor progression through various pathways, however, the role of DHX37, as an important member of the DEAD/H-box RNA helicase family, in hepatocellular carcinoma progression has been less studied." (PMID 37958405, 2023).
lung squamous cell carcinoma (2 papers, 2020 to 2021). "Interestingly, the high expression of DHX37 was associated with favorable prognosis in lung squamous cell carcinoma, rectum adenocarcinoma, stomach adenocarcinoma, uterine corpus endometrial carcinoma, and thyroid carcinoma, which seemed to be not consistent with its role in cancer immune." (PMID 33490273, 2021). "For lung squamous cell carcinoma, thyroid carcinoma, rectum adenocarcinoma, stomach adenocarcinoma, and uterine corpus endometrial carcinoma, DHX37 plays a protective role in their OS but not RFS." (PMID 33490290, 2020).
thyroid carcinoma (2 papers, 2020 to 2021). "Salivary gland carcinoma had 100% missense substitution, and thyroid carcinoma had 85.71%, suggesting that abnormal amino acid sequence of DHX37 may account for tumor development of these two cancers." (PMID 33490273, 2021). "Furthermore, we also found that DHX37 expression weakly to moderately negatively correlated with 28 types of TILs and MHC expression across all human heterogeneous cancers, except in KIRP (kidney renal papillary cell carcinoma), THCA (thyroid carcinoma), and LGG (brain lower grade glioma)." (PMID 33490290, 2020).
Alzheimer disease (1 paper, 2021). A progressive, neurodegenerative disease characterized by loss of function and death of nerve cells in several areas of the brain leading to loss of cognitive function such as memory and language. "Lastly, the 3rd most down-regulated gene, DHX37, harbors a rare frameshift mutation that segregates with Alzheimer’s disease in one family." (PMID 34194426, 2021).
anencephaly (1 paper, 2024). A rare neural tube defect during pregnancy, resulting in the absence of a large portion of the brain and skull in the fetus. "DHX37 is a member of the DEXH family of RNA helicases, and DHX37 mutations have been previously shown to cause 46, XY GD, testicular regression sequence (TRS), or anencephaly." (PMID 38915825, 2024).
anorchia (1 paper, 2020). "In contrast to the range of phenotypes associated with variants in other testis-determining genes, pathogenic variants involving DHX37 are associated with TRS but not anorchia." (PMID 31337883, 2020).
brain malformations (1 paper, 2017). "Additionally, DHX37 has been proposed as a candidate gene for brain malformations, highlighting the importance of RNA helicases in development of the central nervous system." (PMID 28327206, 2017).
cortical dysplasia (1 paper, 2022). "Indeed, a rare frameshift mutation identified in DHX37 has also been linked to AD and novel variants of DHX37 have been linked to structural brain malformations including cortical dysplasia." (PMID 35646086, 2022).
dementia (1 paper, 2021). Loss of intellectual abilities interfering with an individual's social and occupational functions. "Other differentially expressed genes have been previously associated with dementia (ITM2B, MAPT, ZNF267, and DHX37)." (PMID 34194426, 2021).
developmental delay (1 paper, 2021). "Patients carrying DHX37 mutations showed developmental delay and intellectual disability as well as vertebral anomalies." (PMID 34440387, 2021).
germ cell tumor (1 paper, 2025). A benign or malignant, gonadal or extragonadal neoplasm that originates from germ cells. "Notably, the risk of germ cell tumors related to NR5A1 variants may be associated with the severity of the phenotype and variant type, and DHX37 variants may increase cancer risk when considering their function in ribosomal biogenesis, which warrants further investigation." (PMID 40290305, 2025).
hypospadias (1 paper, 2023). Hypospadias is the displacement of the urethral meatus on the ventrum of the penis. "On the other hand, in our recent study reporting on the genetic etiology of hypospadias in 99 cases, no (likely) pathogenic DHX37 variants were identified." (PMID 39659563, 2023).
liver cancer (1 paper, 2020). An epithelial or non-epithelial malignant neoplasm that arises from the liver. "The E2F family, always related to the progression of liver cancer, served as the main transcription factors for DHX37 dysregulation." (PMID 33490290, 2020). "Our study has identified DHX37 as a potential marker of lung and liver cancers, which may guide the development of novel anticancer therapies." (PMID 33490290, 2020).
Primary Immunodeficiency (1 paper, 2023). "Further analysis revealed that the following pathways were activated in samples with high DHX37 expression: cell cycle, chemokine signaling pathway, DNA replication, proteasome, primary immunodeficiency, and T cell receptor signaling pathway." (PMID 37958405, 2023).
prostate carcinoma (1 paper, 2026). A carcinoma that arises from epithelial cells of the prostate gland. "SETD6 KO GO Group 1 is related to cell proliferation and includes DHX37 and COX10, which both are associated with prostate cancer." (PMID 41540805, 2026).
tumor (7 papers, 2020 to 2026). "Multivariate Cox regression showed that tumor status (p = 0.006), pathologic T stage (p < 0.001), and DHX37 level (p = 0.007) were independent risk factors for the OS of HCC." (PMID 37958405, 2023). "In the COX regression model, univariate Cox regression indicated that tumor status (p < 0.001), pathologic T stage (p < 0.001), pathologic M stage (p = 0.017), and DHX37 level (p < 0.001) were risk factors for the OS of HCC." (PMID 37958405, 2023). "High expression of DHX37 is an independent risk factor for poor prognosis in HCC, and DHX37 is expected to be a potential target to inhibit tumor progression." (PMID 37958405, 2023). "We aim to identify the prognostic value of DHX37 associated with tumor microenvironments in cancers." (PMID 33490290, 2020). "Dysregulation of RNA helicases has been implicated in tumourigenesis; however, the clinical significance of DHX37 expression in tumours is still emerging and requires further study." (PMID 42151440, 2026). "The authors found that RNA helicase DHX37 knockout enhances anti-tumour immunity in T cells, showing that DHX37 suppresses cytokine production and T cell activation and that DHX37 interacts with PDCD11 influencing NF-κB activity." (PMID 40650785, 2025). "In particular, TCGA-HCC data analysis revealed that DHX37 was significantly highly expressed in both paired and unpaired tumor tissues." (PMID 37958405, 2023). "Results showed that DHX37 expression was associated with AFP (ng/mL) (p = 0.005), tumor status (p = 0.009), residual tumor (p = 0.017), vascular invasion (p = 0.035), and histologic grade (p = 0.019)." (PMID 37958405, 2023). "Using the UALCAN website, we compared the expression of DHX37 between normal samples and tumor samples in 23 human cancers." (PMID 33490273, 2021). "In the present study, by utilizing data in public datasets, we compared the expression of DHX37 between normal tissues and tumor tissues." (PMID 33490273, 2021). "According to the data in TCGA tumor samples, the copy numbers of DHX37 were positively correlated with TIM3, LAG3 and NCOR2, while they were negatively correlated with PD-L1, RGS16 and TOX." (PMID 33490273, 2021). "Based on multilevel evidence, DHX37 plays an oncogenic role and induces a suppressive tumor microenvironment in LIHC and LUAD." (PMID 33490290, 2020). "The comprehensive analysis indicated that the DHX37 expression had significant correlations with tumor purity in 16 types of cancers." (PMID 33490290, 2020). "Surprisingly, the expression level of DHX37 in LIHC and LUAD is not correlated with tumor purity, indicating that the expression of DHX37 in cancer cells and the tumor microenvironment is equally important." (PMID 33490290, 2020). "DHX37 gene expression was retrieved using the Oncomine database to determine differences between tumor and normal tissues over a cancer-wide range." (PMID 33490290, 2020). "DHX37 expression was examined via the Oncomine database and Tumor Immune Estimation Resource (TIMER)." (PMID 33490290, 2020). "DHX37 was more highly expressed in HCC samples compared to adjacent non-tumor tissues." (PMID 37958405, 2023). "The results suggest that the high expression of DHX37 in HCC may promote tumor progression, which is an important factor affecting tumor prognosis, and is potentially instructive in personalized chemotherapy and immunotherapy for HCC." (PMID 37958405, 2023). "First, we found that DHX37 was highly expressed in most tumor tissues, including HCC." (PMID 37958405, 2023). "The relationship between DHX37 and tumor-related immune genes was also investigated." (PMID 33490273, 2021). "Besides, nonsense mutation, inframe insertion, inframe deletion, and frameshift deletion were observed in various tumor types, indicating that structural and functional changes of DHX37 are vital to tumor initiation and progression." (PMID 33490273, 2021).